EGFR (epidermal growth factor receptor)
Diseases named in the same sentence as EGFR in open-access papers (continued):
Sharing a sentence is not in itself a finding about the gene and the disease.
tumor (continued). "Such correlations suggested that the amplification of EGFR and genome instability might have occurred concurrently and that they were accumulated gradually and possibly required for tumor cells to sustain their growth under the pressure of drug selection." (PMID 34385540, 2021). "Interestingly, in this tumor, the dependence on the primary oncogene, EGFR, was maintained throughout the evolution of acquired resistance." (PMID 34642436, 2021). "The inhibition of the mTOR signaling pathway in tumors by zotarolimus reduced TGF-β, CD44, VEGF, and EGFR expression, which could decelerate tumor cell migration and invasion in cancer metastasis." (PMID 33925400, 2021). "Interfering with TRPM2-AS expression could inhibit tumor formation, reduce the expression of EGFR and Ki67, and promote tumor cell apoptosis." (PMID 34394080, 2021). "Similarly, EGFR upregulation was also observed in the H292/ER xenograft tumor tissues compared to that of their parental cells in SCID mice." (PMID 34155348, 2021). "EGFR inhibition is a common targeted therapy for EGFR over expressing tumours." (PMID 33597819, 2021). "Quantification of the interaction of receptors in cancer cells from patients might be worth considering in future studies of HER2 and EGFR (over-) expressing patient tumor cells." (PMID 34831465, 2021). "Furthermore, GSEA revealed several of the GBM associated signaling pathways to be enriched in the low SRY expressing tumors, for example, EGFR, one of the key tumor regulators, aberrant especially in the classical subtype of GBM." (PMID 33807423, 2021). "Notably, treatment with 10 mg/kg of each individual mAb was less effective at inhibiting tumor growth than treatment with anti-EGFR/VEGFR2 BsAb." (PMID 33804477, 2021). "The tumor had apparently favorable staging, T1aN0M0, and did not contain EGFR mutation or ALK rearrangement according to laboratory reports." (PMID 33407806, 2021). "Furthermore, the sidedness of primary tumours also determines the efficacy of targeted therapy in treating mCRC, as is the case for anti-epidermal growth factor receptor (EGFR) agents." (PMID 34188197, 2021). "Therefore, seeking therapeutic strategies to increase the sensitivity to EGFR-TKIs of tumor cells is urgently needed." (PMID 34054543, 2021). "Another main feature of Notch3 signaling is to induce tumor resistance against several kinds of chemotherapeutic drugs, including doxorubicin, platinum, taxane, epidermal growth factor receptor (EGFR)–tyrosine kinase inhibitors (TKIs) and gemcitabine (See in Notch3 and Drug Resistance)." (PMID 34195229, 2021). "It is therefore reasonable to conclude that c-MET/EGFR are important biomarker signatures of tumorigenesis, tumor immune invasion, and poor prognoses, and thus can serve as attractive targets for the development of immune/chemotherapeutic strategies against CRC." (PMID 34512327, 2021). "In addition, there is intercellular EGFR protein transfer from tumor-derived exosomes to endothelial cells." (PMID 34680445, 2021). "AFM24 NK-cell–engaging bispecific antibodies to target EGFR-expressing tumor cells irrespective of their mutational status." (PMID 33953710, 2021). "Previous research suggested that miR-21, miR-27a, and miR-181a may act as tumor-promoting miRNAs in NSCLC, and an increase in their circulating values could be associated with EGFR-TKI resistance." (PMID 34208765, 2021). "Studies have shown that some downstream factors of the EGFR pathway, such as mitogen-activated protein kinase (MAPK), and phosphatidylinositol-3-kinase (PI3K), can adjust the high expression of VEGF, resulting in tumor progression and metastasis, and acquired EGFR-TKI resistance." (PMID 34575576, 2021). "This is well illustrated by Ivermectin (CAS number: 70288-86-7), which potentiates the activity of the anti-androgen receptor and anti-EGFR drugs in prostate and EGFR/HER2-driven tumor models, and also activates GABA-A receptor activity, hence producing neurologic toxicity." (PMID 33923911, 2021).
tumor (continued). "Interestingly, in the model P8X20, the expression level of 7 markers (i.e., Ki67, KRT5/6, KRT20, 34βE12, PD-L1, EGFR, and Nectin4) was exactly similar between the patient tumor and the next generations." (PMID 35432811, 2021). "In addition, we attempted to clarify the impact of tumor lesion-related factors and bronchoscopic technical factors on EGFR-testing outcomes." (PMID 33828971, 2021). "Exosomes derived from drug‐resistant cells may play a crucial role in EMT and resistance to osimertinib in the tumor microenvironment of EGFR‐mutant NSCLC." (PMID 33939301, 2021). "The mechanism of EGFR upregulation in tumor endothelial cells could be attributed to EGF secreted by cancer cells." (PMID 34680445, 2021). "Interestingly, tumor-derived EVs isolated from serum recapitulate the genetic aberrations present in primary tumors, as the presence of the mutant EGFR and EGFRvIII in glioblastoma or MYC amplification in medulloblastoma." (PMID 34199799, 2021). "In the case of PE/CA-PJ15 cells harboring the R521K EGFR mutation, cetuximab did not affect tumor growth." (PMID 34257586, 2021). "In all patients with wild type EGFR tumors, serum PD-L1 levels correlated with tumor PD-L1 level (R = 0.35, p = 0.004) and the number of CD8+ TILs (R = 0.26, p = 0.034), while tumor PD-L1 levels tended to be correlated with the number of CD8+ TILs (R = 0.21, p = 0.083)." (PMID 33837261, 2021). "Similarly, the same 5 mg/kg/day dose level of SH-1028 was sufficient to induce profound and sustained tumor shrinkage in both NCI-H1975 and PC-9 xenograft models with EGFR mutations." (PMID 33986687, 2021). "Intrinsic alterations of tumours greatly contribute to resistance to anti-EGFR targeted therapy." (PMID 34663410, 2021). "EGFR testing needs a good quality sample with enough tumor cells and thus, may require multiple attempts to be conclusive." (PMID 33652831, 2021). "Moreover, LR004-VC-MMAE also killed tumor stem cells in EGFR-positive TNBC cells and impaired their tumorsphere-forming ability." (PMID 34879870, 2021). "EGFR/BRAF inhibition may render a tumour responsive to checkpoint blockade by temporarily converting an MSS tumour into an immunogenic MSI tumour and igniting a lymphocytic immune response." (PMID 34302062, 2021). "Moreover, tumor patients with EGFR amplification demonstrated worse prognosis compared with patients without EGFR amplification (P < 0.0001), suggesting that EGFR amplification was a biomarker correlated with the clinical outcomes across different tumor types." (PMID 33959491, 2021). "Furthermore, the EGFR (R108K) truncal alteration can be effectively targeted with available therapies to inhibit tumor growth, despite the presence of additional drivers." (PMID 34568716, 2021). "In addition, the immunohistochemical analysis indicated that FGFC1 treatment decreased the expression of Ki-67, a marker for tumor cell proliferation, and significantly reduced EGFR phosphorylation in tumor cells which were consistent with the in vitro study." (PMID 35126111, 2021). "By retrieving tumor purity scores computed by integrating independent lines of evidence, we found that indeed TCGA samples derived from KRAS-mutated lung tumors had higher purity scores than EGFR-mutated tumors." (PMID 34344431, 2021). "Mechanistically, HNK accelerated the nuclear translocation of glucocorticoid receptor (GR) and promoted mitogen-inducible gene 6 (MIG6)/ERBB receptor feedback inhibitor 1 (ERRFI1) expression, leading to EGFR degradation and thereby resulting in robust tumor suppression." (PMID 33806040, 2021). "Moreover, protein expression levels of SQSTM1 were positively correlated with that of EGFR in tumor tissues of OSCC patients (r = 0.136, p < 0.001)." (PMID 34830108, 2021). "To explore whether ILT4 was upregulated by EGFR activation, we retrospectively analyzed ILT4 expression differences in EGFR wild-type and mutant tumor tissues from 80 NSCLC patients." (PMID 33537094, 2021).
tumor (continued). "Taken together, these data suggested that RhoB might function as a tumor suppressor in HER2/EGFR-double positive breast cancers." (PMID 34187934, 2021). "(ii) High EGFR expression in many tumors may lead to radiotherapy insensitivity and reduce tumor control rate, resulting in tumor recurrence." (PMID 34128318, 2021). "Preclinical evidence has supported a radiosensitizing role for EGFR inhibition and indeed, the addition of cetuximab to RT in patients with head and neck squamous cell cancer was shown to improve tumor control and overall survival compared with radiation alone." (PMID 34733787, 2021). "This is particularly the case for patients receiving a third-generation EGFR TKIs who may present many different genetic alterations on tumor progression." (PMID 33922637, 2021). "When the BsAb sequence is added after the EGFRvIII CAR-T plasmid sequence, CAR-T cells can target EGFRvIII-positive tumor cells, and the released BsAb can recruit T cells to form a bridge, thereby killing EGFR-positive tumor cells that have lost the EGFRvIII antigen." (PMID 34025638, 2021). "According to these findings, targeting both kinase-dependent and independent functions of EGFR could be necessary for an effective strategy to overcome tumor resistance to conventional anti-EGFR therapies." (PMID 33451055, 2021). "The distribution of EGFR and ErbB2 expression in the xenograft tumor has been previously reported." (PMID 34832857, 2021). "LC-C may promote radiation induced anti-tumor effect by increasing the expressions of ERRFI1 and associated with EGFR and STAT3 signaling pathways." (PMID 33869036, 2021). "Knocking down ELF3 expression attenuates activation of NF-κB pathway genes in two LUAD cell lines A549 (KRAS mutation) and NCI-H1975 (EGFR mutation L858R), supporting the conclusion that inflammatory cytokines (e.g. IL1B) can regulate tumor cell proliferation and anti-apoptosis through ELF3 action." (PMID 33144684, 2021). "Similarly, an analog of SNX-2112 was also found to inhibit tumor growth in a mutant EGFR NSCLC model." (PMID 34475996, 2021). "Tumor uptake in mice bearing control MDA-MB-435 xenografts was low (4.0 ± 1.44%IA/cc) at the end of 120 h which confirms specific uptake 111In-nimotuzumab to EGFR positive DLD-1 xenograft model." (PMID 33535661, 2021). "Gain-of-function mutations of ubiquitin-specific protease (USP) 8, USP48, and BRAF genes may subsequently cause overexpression of epithelial growth factor receptor (EGFR), and enhance POMC transcription, cell proliferation, and tumor growth." (PMID 33986726, 2021). "Likewise, another signaling axis, EGFR/miR-338-3p/EYA2, has been linked by a recent study to tumor growth and lung metastasis." (PMID 34206026, 2021). "One model, DFCI81, was established from the tumor-derived cell line of a patient who developed acquired resistance after an initial long-term response to treatment with EGFR-targeted therapy, whereas the other two models, DFCI161 and DFCI307, exhibited de novo resistance to EGFR TKI." (PMID 34516823, 2021). "This gene list partitioned the mutated tumor samples into three sample clusters: S1 including 95% (39/41) of EGFR-Ex18/19/21mut samples, S2 including 78% (18/23) of ERRB2-Ex20mut samples and S3 including 100% (8/8) of EGFR-Ex20mut samples." (PMID 34487971, 2021). "Likewise, high levels of T cell recruiting and activating IFN-γ induced IP-10/CXCL10 chemokine was induced by EGFR hCART41BBζ, during overnight co-culture with tumor cells at 1:1 E:T ratio compared other hCART, COATC and BATs." (PMID 34290709, 2021). "This study hypothesized that combination of CHM and EGFR-TKIs may prolong PFS, increase tumor response, improve performance status, and reduce toxicities in advanced NSCLC patients harboring EGFR sensitizing mutation, compared with use of EGFR-TKIs alone." (PMID 34512332, 2021).
tumor (continued). "Also, in the presence of CAFs, tumor cells show reduced sensitivity to cetuximab, a monoclonal antibody therapy targeting the epidermal growth factor receptor (EGFR)." (PMID 34660589, 2021). "Moreover, tumor-promoting functions were blocked by anti-EREG antibodies or an EGFR-tyrosine kinase inhibitor (EGFR-TKI, gefitinib or erlotinib) in NSCLC." (PMID 34884633, 2021). "One may speculate this to be a result of a smaller fraction of EGFR-expressing tumor-derived sEVs in the liquid biopsy in PE020 than in PE011, which in turn may be a consequence of the different treatment lines among these two patients." (PMID 33671772, 2021). "However, treating RAC1B-depleted tumour cells with an EGFR inhibitor led to a significant reduction in the clonogenic growth of these cells." (PMID 33879799, 2021). "In HCC, EGFR is overexpressed in liver macrophages, where it has a tumor-promoting role." (PMID 34579396, 2021). "Overexpression of EGFR has been reported in a variety of tumor types." (PMID 34425750, 2021). "Functioning as a tumor suppressor, high level of YTHDF2 could inhibit the proliferation and neoplasia by degrading EGFR mRNA of HCC cells in an m6A-dependent manner." (PMID 34747720, 2021). "Such a finding dovetails the results from other studies in the field, which collectively show a lack of CD8 T-cell infiltration in EGFR-mutated tumours." (PMID 35052732, 2021). "We hypothesized that SG potentially mediates an anti-tumor effect similar to cetuximab via interacting with the EGFR extracellular domain." (PMID 33946151, 2021). "Additionally, we performed cellular binding assays using EGFR-overexpressing tumor cell line A431 and EGFR-negative ExpiCHOTM cells." (PMID 34759924, 2021). "Additionally, sh-SOX2 treatment decreased mRNA expression of SOX2, CCAT1, EGFR, and miR-222-5p in tumor isolated from nude mice, but increased the mRNA expression of CYLD." (PMID 33952719, 2021). "Interestingly, EGFR downstream signalling inhibition is a promising strategy in diverse tumor types by inducing MHC-II in APCs and breaking down tolerance." (PMID 33610187, 2021). "Some evidence suggests that the T790M clonality level at baseline, i.e., the size of the T790M-positive population of tumor cells, might influence the response to third-generation EGFR-TKIs." (PMID 34638411, 2021). "Reducing tumour formation while increasing EGFR activation seems counterintuitive." (PMID 34610265, 2021). "In the 24 tumours without TERTp mutation, MLPA showed EGFR amplification in 3 AAs, and no tumours with + EGFR/− PTEN." (PMID 34257410, 2021). "In 1989, at the age of 30, José moved to MSK to work in the clinic with Larry Norton and in the laboratory with John Mendelsohn to investigate the anti-tumor activity of therapies that block the epidermal growth factor receptor (EGFR) and HER2 on cancer cell lines." (PMID 33962670, 2021). "Patients harbouring EGFR mutation positive tumours had a longer median overall survival; however, it was not possible to individualise outcomes, according to patient age." (PMID 34567264, 2021). "In addition, the TUNEL assay confirmed that SAE increased apoptosis rates in tumor cells and decreased p-EGFR and increased cleaved-caspase 3 in a dose-dependent manner." (PMID 34094906, 2021). "We chose the SCC74A and SCC74B cell lines for this study because previous work demonstrated elevated HER2 and EGFR in the more-aggressive SCC74B cell line (derived from a 1-year recurrence) compared to SCC74A cells (derived from the primary tumor at the same site)." (PMID 34628733, 2021). "These molecular events induce EGFR degradation and anti-tumor activity in cSCC." (PMID 34689164, 2021). "To test whether the downregulation of EGFR in tumor spheres was dependent on the activation of Notch1, we performed binding assays of parental cells (H1975 and HCC827) to plates coated with an increasing concentration of the DLL4 Notch agonist." (PMID 33922104, 2021).
tumor (continued). "Furthermore, activation of the EGFR signaling pathway was proposed as a rational target for anti-tumor drugs." (PMID 34753514, 2021). "Moreover, cetuximab has anti-body-dependent cell-mediated cytotoxicity, owing to its IgG1 isotype, as it directs cytotoxic immune-cells against EGFR-expressing tumor cells." (PMID 34440249, 2021). "Furthermore, other studies have also used ERAs as cancer therapeutic drugs, diminishing the effect of ET-1 on tumour progression, by constraining epidermal growth factor receptor and blocking angiogenic effects." (PMID 34367381, 2021). "Previous meta‐analysis proved that adjuvant treatment with EGFR‐TKIs can reduce the probability of tumor recurrence and prolong DFS with fewer adverse events, indicating that they can provide an alternative option to adjuvant chemotherapy in patients with EGFR‐mutated NSCLC." (PMID 33660941, 2021). "They proposed that ALDH1A1 high/CD44 low/EGFR low tumor cells may be stationary and quiescent, while ALDH1A1−/CD44 high/EGFR high cells may be invasive and migratory." (PMID 34359786, 2021). "Moreover, miR-143 and miR-145 have been well established to exert tumor-suppressive effects and are beneficial for the efficacy of anti-EGFR treatment in CRC, whereas miR-31-3p comes to the opposite." (PMID 35111681, 2021). "Taking EGFR, PI3K, AKT, and NFκB together, Our finding was in accordance with the report that EGFR activation could further trigger the PI3K-AKT-NFκB signaling axis and eventually cause tumor cells proliferation." (PMID 33746755, 2021). "Subsequent studies have established the benefit of adding anti-EGFR antibodies to first-line doublet therapies is also limited to tumours without mutations in other RAS exons." (PMID 34407800, 2021). "Additionally, everolimus or AZD8055 can increase EGFR activation in tumor cells, leading to drug resistance." (PMID 34178634, 2021). "Next, we addressed whether SGLT1 inhibitors can enhance the therapeutic efficacy of EGFR TKIs in tumor xenograft mouse models." (PMID 34155348, 2021). "The mTOR blockade, therefore, interferes at multiple levels with tumor growth, and the dual targeting of EGFR and mTOR may have a greater effect with respect to the administration of a single target." (PMID 34769263, 2021). "Combined with EGFR inhibition, prednisone is significantly superior to etanercept or thalidomide in durably suppressing tumor growth in multiple mouse models, indicating that a broad suppression of adaptive signals is more effective than blocking a single component." (PMID 34853306, 2021). "In particular, cfDNA could be used as a non-invasive method to detect EGFR mutations in patients with NSCLC, with similar accuracy to that of tumor tissue biopsies." (PMID 34722241, 2021). "Single-cell analysis showed that the simple coexistence of EGFR mut and EGFR wt cells within the tumor may attenuate the response to EGFR TKI, since only tumor cells harboring EGFR sensitizing mutations display responsiveness to TKI treatments." (PMID 33572284, 2021). "Thus, ILT4 in EGFR-activated tumor cells promoted the accumulation and M2-like polarization of TAMs and facilitated TAM-induced T cell dysfunction." (PMID 33537094, 2021). "The highly enriched pathways were MAPK signaling pathway, Rap1 signaling pathway, Ras signaling pathway, EGFR tyrosine kinase inhibitor resistance, ErbB signaling pathway, and so on, which were well-known signalings for tumor growths and metastasis, indicating the protumor immune microenvironment." (PMID 33790969, 2021). "In addition, tumor-derived exosomal circRNA_102481 was identified as a key circRNA in the EGFR-TKIs resistance process." (PMID 33952725, 2021). "In addition, our present data demonstrated that loss of PTK7 expression in TNBC cells results in a downregulated EGFR/Akt signaling and reduced tumor growth in MBA-MD-468 TNBC cancer xenografts." (PMID 34367983, 2021).